TNF (tumor necrosis factor)
Diseases named in the same sentence as TNF in open-access papers (continued):
Sharing a sentence is not in itself a finding about the gene and the disease.
diabetes (continued). "Emodin-loaded Poly-PEGMA-DMAEMA-MAM nanoparticles have shown efficacy in alleviating diabetic neuropathic pain by inhibiting purinergic P2X3 receptor expression, reducing TNF-α levels, and suppressing ERK1/2 activation in the dorsal root ganglia of type 2 diabetic rats." (PMID 39942768, 2025). "Interestingly, PDB and flavone treatment significantly inhibited diabetes-mediated increase in levels of IL-1β, IFN-γ, TNF-a, and IL-6." (PMID 40486272, 2025). "After adjusting for hypertension, diabetes, triglyceride levels, gender, and age, Student t tests covariance confirmed significant differences in the enrichment levels of TWEAK, TNF-α, IL-10, and IL-4 of patients in case group (PTWEAK = .017, PTNF-α < .001, PIL-10 = .010, PIL-4 = .016)." (PMID 40629651, 2025). "Here, we found that intravitreal injecting porous Se@SiO2 nanospheres could significantly suppress the expression of TNF-α, IFN-γ, and IL-1β in the retina, which was increased by diabetes." (PMID 38321393, 2024). "Meanwhile, vanillic acid has been found to suppress the overexpression of inflammatory mediators such as NF-κB, TNF-α, and COX-2 and also promotes the up-regulation of nuclear factor-erythroid 2-related factor 2 (Nrf-2) proteins, which play a crucial role in diabetes and diabetic nephropathy." (PMID 39334723, 2024). "We aimed to homogenize our study group in terms of HbA1c levels rather than compare their current blood glucose levels or diabetes treatments, because we wanted to evaluate the long-term effects of TNF inhibitors." (PMID 38842591, 2024). "Németh Zoltán H found that NECA could prevent the development of diabetes in STZ and cyclolinamide-induced diabetic mouse models, strongly suppressed expression of the pro-inflammatory cytokines TNF-α, macrophage inflammatory protein 1, IL-12, and IFN-γ." (PMID 38895119, 2024). "Intriguingly, we found that NOD1 depletion in hematopoietic cells does not exert any influence on diabetes-induced alterations in TNFα and IL10, underscoring the intricate nature of the inflammatory response operating within the diabetic retina." (PMID 38336763, 2024). "Given that chronic inflammation played an important role in the onset and progression of diabetes and related complications, the impact of DPP-4i on TNF-alpha might produce an additional benefit in diabetic patients." (PMID 38997754, 2024). "PCI Diabetes patients exhibit less correlation with TNFα and IL8 secretion (r2 = 0.46, p = 0.0001) than PCI without diabetes (r2 = 0.63, p = 0.0001)." (PMID 38216681, 2024). "In comparison with non-diabetic control mice, mice with diabetes demonstrated elevated levels of tumor necrosis factor-alpha (TNF-α) in the pancreas." (PMID 39003280, 2024). "In contrast to previous observation, the present study revealed that there was no significant recovery of diabetes corresponding to TNF-α and ICAM-1 in serum and tears." (PMID 39279894, 2024). "The present study investigated the effects of Andaliman fruit extract on tumor necrosis factor-alpha (TNF-α) and transient receptor potential ankyrin-1 (TRPA-1) levels in type 2 diabetes mellitus (T2DM) mouse models induced with streptozocin (STZ) and a high-fat diet (HFD)." (PMID 39101085, 2024). "PHE significantly improved the diabetes state in a dose-dependent way by decreasing leptin and increasing GCK, most likely via reducing ROS generation and inflammatory molecules like IL-6 and TNF-α." (PMID 38234664, 2024). "In a cross-sectional study that evaluated the circulating level of FABP4 in 43 morbidly obese and 38 lean women with no diabetes, there was a significant association between FABP4 and circulating CRP, HOMA-IR, and tumor necrosis factor (TNF)." (PMID 38731797, 2024). "Later (16 weeks) hUC-MSC injection also resulted in reduction of diabetes-associated renal abnormalities and serum TGF-β1 but not of serum IL-6 and TNF-α." (PMID 38443965, 2024).
diabetes (continued). "Diabetes patients have shown a higher concentration of TNF-α in plasma than non-diabetic, where a strong correlation was found between TNF- α and severity of DR." (PMID 39279894, 2024). "Based on our analysis of 21 RCTs, we found that supplementing with L-carnitine can lead to significant improvements in various health markers, such as TG, LDL, FBG, HbA1c, HOMA-IR, CRP, TNF-α, weight, BMI, BFP, and leptin levels in patients with diabetes and glucose intolerance." (PMID 39085907, 2024). "In logistic regression models adjusted for treatment of diabetes conducted in the PSM cohort, IL-9 (OR 1.654, 95%CI 1.129–2.422, p = 0.010), IL-17 (OR 1.948, 95%CI 1.259–3.012, p = 0.003) and TNF-α (OR 1 2.051, 95%CI 1.286–3.272, p = 0.003) were independently associated with CAD." (PMID 39091640, 2024). "In addition, mRNA expressions of inflammatory markers IL-1β and TNF-α were negatively correlated with protein levels of LC3B-II and positively correlated with SQSTM1 in PBMCs from type 2 diabetes mellitus patients." (PMID 36994103, 2023). "We have long wondered why aberrant BMDCs, despite the non-physiological expression of proinsulin and TNF-α, are not considered “a foreign substance” to be eliminated by the immune system in the context of diabetes." (PMID 37311905, 2023). "Moreover, administration of EPE to both S-NOD and Cyp-NOD mice decreased the expression levels of TNF-α and IFN-γ, and markedly decreased the severity degrees of insulitis and immunoreactive (IRS) scores to lower the incidence of diabetes." (PMID 37373070, 2023). "For this pilot study, we examined three different therapies known to either stimulate or preserve insulin secretion in people with diabetes and residual C-peptide: namely, liraglutide, a GLP-1R agonist; verapamil, a calcium channel blocker; and golimumab, a TNF-α blocking agent." (PMID 38096190, 2023). "Despite overwhelming evidence in favour of TNF-α having a critical role in regulating inflammation and insulin-action, the translation of basic research findings with TNF-α-targeted neutralisation in diabetes showed disappointing results." (PMID 37627482, 2023). "A double-blind, placebo-controlled clinical trial in 50 type 2 diabetes mellitus patients showed that the treated group receiving Iranian propolis (1000 mg/day) for 90 days showed a significant reduction in serum levels of CRP, TNF-α, glycosylated hemoglobin, and insulin." (PMID 37111285, 2023). "Subsequently, MIN6 cells were treated with a cytokine mixture of TNF-α, IL-1β and IFN-γ in the presence or absence of UC, and verapamil, a TXNIP inhibitor for prevention of beta cell loss and diabetes development, was used as a positive control in this study." (PMID 38040681, 2023). "However, recent studies have demonstrated through biological and proinflammatory analyses of TNF-α, IL-6, CRP and MMP that this cytokine storm condition directly influences systemic conditions or diseases, such as diabetes and CVD." (PMID 36984510, 2023). "TNF serum expression was also higher in patients with diabetic polyneuropathy compared to diabetes without polyneuropathy." (PMID 36604634, 2023). "The level of TNF-α, IL-6, and IL-1 β expression was increased in both groups (with and without diabetes) during the use of CSs, while with HTPs, IL-1β and TNF-α increased significantly only in the diabetic group." (PMID 37794516, 2023). "Following adjustment for age, sex, and diabetes duration, the associations remained robust for PAI-1, TF activity, and Fibrinogen, but not TNF-α." (PMID 36495341, 2023).
diabetes (continued). "In contrast, unlike glucocorticoids, diabetes treatment with high-dose salicylates, anti-cytokine antibodies (TNF and IL1β) or gene therapy approaches targeting NF-κB regulatory loops (e.g. A20) do not risk directly inhibiting basal NF-κB activity." (PMID 37311878, 2023). "Diabetes not only impairs antioxidant integrity but also initiates neuroinflammatory reactions by activating the nuclear transcription factor NfκB, which stimulates IL6, IL-1β, and TNF-α pro-inflammatory cytokines." (PMID 38105928, 2023). "The production of ICAM-1 in diabetes mellitus is also increased by nonperfusion, ischemia, and elevated TNF-α levels." (PMID 37373315, 2023). "TNF-α levels were significantly higher in rats with STZ-induced diabetes compared to animals without diabetes." (PMID 37189822, 2023). "In both cohorts, the most common CCI disorder was rheumatic diseases (No-TNFα: 28.6%, Yes-TNFα: 49.2%), followed by chronic pulmonary disease (19.6% and 11.4%) and diabetes (16.3% and 11.3%)." (PMID 36902722, 2023). "The exposure under scrutiny was TNF-α levels, with a comparator group consisting of individuals with diabetes mellitus without neuropathy or healthy volunteers." (PMID 38179375, 2023). "Previous studies have confirmed that the level of cellular inflammatory factors such as tumor necrosis factor-α (TNF-α), interleukin-6 (IL-6) and C-reactive protein (CRP) was increased in elderly patients with diabetes, and anti-inflammatory factors such as IL-10 were reduced." (PMID 38273819, 2023). "Our research results showed that 28 ginsenosides in ginseng might be against diabetes mellitus by modulating related proteins such as VEGFA, Caspase 3, and TNF-α." (PMID 36646777, 2023). "The induction of diabetes mellitus leads to the initiation of the inflammatory process and the release of pro-inflammatory cytokines such as IL-2 and TNF-α and does not produce any change in the levels of IL-4, IL-5, and INF-ɣ." (PMID 37842429, 2023). "Our results showed that patients with diabetes presented higher IL-10 and TNF-α gene expression compared to those without diabetes, suggesting an increased inflammatory activity." (PMID 37189738, 2023). "In a comparison with the non-TNF inhibitor group, younger age, diabetes mellitus and absence of ILD were factors influencing the prescription of JAKis." (PMID 36626396, 2023). "A previous study showed that rats with diabetes produced significantly higher levels of interleukin (IL-1) and tumor necrosis factor-alpha (TNF-α) than those without diabetes, suggesting the involvement of pro-inflammatory cytokines in the development of DN." (PMID 37047505, 2023). "Rats treated with diabetes and DEPs reported increased TNF-a expression compared to rats not treated with DEPs, and the results of this study also showed elevated TNF-α expression in group 1, a group treated with DEPs, while rats treated with probiotics and KRG had reduced TNF-α expression." (PMID 37374359, 2023). "We found that diabetes induced strong increases in pancreatic IL-1β and TNF-α, but not IFN-γ, at the protein level at the 4-week time point, and all cytokines were further elevated at the 8-week time point." (PMID 37040355, 2023). "In addition, the TNF-α, NF-κB and MAPK levels and acute phase reactants were significantly higher in the diabetes group compared to the prediabetes group." (PMID 38136648, 2023). "To identify lncRNAs that may play a role in the diabetes-impaired angiogenesis in ECs, we examined RNA sequencing (RNA-seq) data sets from human ECs subjected to high glucose (HG) (GSE135357), TNF-α (GSE163433), and hypoxia (2% O2) (GSE136912), respectively." (PMID 36512424, 2023). "Comparing the immunological makers in both groups, subjects in the DFU group showed a lower ApoA1 and IL-10 but higher TNF-α when compared to patients with diabetes without foot ulcers (Group- I)." (PMID 35836916, 2022).
diabetes (continued). "Our results indicate that ET-1 may play a critical role in mediating myopathy and adipose inflammation through the release of IL-6, TNF-α, or adipokines visfatin through PI3K/Akt/miR-let-7g-5p pathways in elderly individuals with diabetes." (PMID 35468098, 2022). "The other variables, gender, BMI, duration of diabetes, hypertension, and TNF-α, were not significant in this model for the study population." (PMID 35836916, 2022). "Previous studies analyzed the relationship between VF and chronic diseases, including diabetes and CVD, and demonstrated that visceral adipose tissue generates high levels of proinflammatory cytokines, including interleukin-6 and tumor necrosis factor-alpha (TNF-α)." (PMID 36555992, 2022). "The study confirmed that the greater prevalence of red complex bacteria and TNF-α in CKD patients, with diabetes as one of the confounding factors, has emerged as one of the major contributors for the progression of periodontitis, which paves the way for perirenal continuum." (PMID 35336824, 2022). "Experiments show that GMP can reduce the levels of IL-6, TNF- α, and CRP, increase the level of IL-10, and then alleviate the inflammatory reaction induced by diabetes and repair the phenomenon of hepatocyte lysis and inflammatory cell infiltration in mice, so as to improve the liver injury." (PMID 35399678, 2022). "Regular exercises have been shown to increase the release of anti-inflammatory cytokines and they lead to a reduction in pro-inflammatory cytokines, e.g., TNF-α and interleukin 1β (IL-1β), interleukin 6 (IL-6), interleukin 18 (IL-18), CRP, which play a role in the pathogenesis of diabetes." (PMID 36555387, 2022). "Moreover, ZER attenuated the upregulation of tumor necrosis factor (TNF-α), interleukin-1 (IL-1), and interleukin-6 (IL-6) induced by diabetes." (PMID 35949312, 2022). "There are very low levels of ROS generated from the mitochondria of renal cells, but these levels can be significantly increased in response to certain factors, such as angiotensin II, TNF-α, LDL, and NADPH oxidase, as well as pathological conditions, such as diabetes." (PMID 36547068, 2022). "Additionally, TNF-α, IL-6 and MCP-1 have been observed in the serum of individuals with diabetes and elevated production of TNF-α leads to increased serum glucose concentrations." (PMID 36292751, 2022). "When compared to people with type 2 diabetes mellitus without nephropathy, subjects with DN had higher levels of uMCP-1 and plasma TNF, and they found a significant link between uMCP-1 and plasma TNF." (PMID 36239103, 2022). "Additionally, PISA was identified as a potentially useful index for evaluating diabetes status in patients with diabetes and periodontal disease because of its strong correlation with HbA1c, hs-CRP, and TNF-α." (PMID 36140045, 2022). "Further, islets isolated from diabetes‐resistant (CA‐EGFR overexpression) animals were resistant to the cytotoxic effects of the pro‐inflammatory cytokines (IL‐1β, tumor necrosis factor [TNF], and IFNγ) that are primarily responsible for β‐cell destruction in T1D." (PMID 35191175, 2022). "In the present study, waist circumference, BMI, systolic blood pressure, diastolic blood pressure, FBG, GHb, TC, TG, HDL-C, and TNF-α values were greater and GLP-1 expression levels were lower in patients with diabetes mellitus combined with metabolic syndrome." (PMID 35360475, 2022). "Diabetes and hypertension lead to structural and functional changes of the neurovascular unit, alter collaterals, and elevate MMP-9, ROS, and proinflammatory cytokines (TNF, IL-1β, and IL-6)." (PMID 34054705, 2021). "Diabetes related biomarkers, gastric inhibitory polypeptide (GIP), leptin, glucagon, and inflammatory cytokines interleukin 4 (IL-4) and IL-5, 10 and 12, IFN-g and TNF-α were significantly affected by HFB diet." (PMID 34441468, 2021).
diabetes (continued). "Therefore, the positive effect of 11,12 EET on wound healing in diabetes might not be linked to alteration of the expression of TNF-α in the model we used but could be linked to an alteration of its downstream mechanisms, which would be interesting to investigate in future studies." (PMID 34769092, 2021). "RS2 supplementation did not improve cardiometabolic health in adults with pre-diabetes, although it does reduce TNF-α concentrations." (PMID 35096939, 2021). "Increased levels of IFN-γ and TNF-α in the vitreous have been found in patients with diabetes compared to non-diabetic patients." (PMID 34780524, 2021). "Moreover, elevated levels of C-reactive protein (CRP), tumor necrosis factor-α (TNF-α), IL-6, IL-18, and IL-1β were reported among patients with type 2 diabetes mellitus displaying features of the insulin resistance syndrome." (PMID 34917685, 2021). "Regarding the Th1 cytokines, patients with diabetes indicated markedly higher IL-2R levels in week 1 and 2 after admission, IL-1β in week 3, and TNF-α in week 1–3 compared to patients without diabetes." (PMID 33776910, 2021). "A 10-year CVD follow-up study of Caucasian adults reported LAP to be an independent predictor of CVD; the association of LAP with CVD remained significant, even after adjusting for hypertension, diabetes, physical activity, HTG, and pro-inflammatory cytokines (C-reactive protein, IL-6, TNF-α)." (PMID 35010926, 2021). "Immediate insulin treatment did not result in protection against diabetes-related alterations of TNFα expression in any of the gut segments." (PMID 34572059, 2021). "The diabetes-induced HMGB1 shuttling from the nucleus with subsequent activation was triggered mainly by the persistent hyperglycemia and the inflammatory agents, such as IL-1β and TNF-α." (PMID 33915770, 2021). "The results of KEGG enrichment indicated multiple signaling pathways, including AGE-RAGE signaling pathway in diabetic complications, HIF−1, TNF, adipocytokine, NF-kappa B, PPAR, and other diabetes-related signaling pathways involved in the treatment of NAFLD by using saffron." (PMID 34179049, 2021). "Increased intra-renal FcER1activation in infiltrating mast cells in a patient with diabetes may promote the release of many inflammatory mediators, including TGF-β, TNF-α, IL6, Tryptase, IL1, which can then subsequently drive the development of renal fibrosis." (PMID 34925339, 2021). "TGF-β/IL18 independently predicted the SRA1 expression in people without diabetes and in the total study population, while TNF-α/IL-2RA predicted SRA1 only in people with diabetes." (PMID 34685582, 2021). "After treatment, the serum levels of apelin, TNF-α, and FBG reduced in patients with diabetes; moreover, apelin levels were found significantly lower in the DPN-B group as compared to the DPN-A group, while some NCV values significantly increased in the DPN-B group." (PMID 33907154, 2021). "Therefore, the reduced levels of TNF- α and CRP in patients with type 2 diabetes mellitus complicated with moderate-to-severe chronic periodontitis are linked to the balance of blood glucose." (PMID 33832490, 2021). "One study conducted among obese individuals without diabetes reported that prolonged (6 months) TNF inhibition significantly decreased fasting glucose and increased adiponectin, probably reflecting improved insulin sensitivity." (PMID 34616762, 2021). "Age-affected 18 variables include comorbidity, hypertension, diabetes, lymphocyte, CD4+ and CD8+ T cells, IL8, TNFα, eGFR, hemoglobin, albumin, CK-MB, onset to admission, onset to PCR negative, discharged, secondary infection, acute kidney injury, and acute liver injury." (PMID 34025688, 2021). "Furthermore, ADP, TNF-α and IL-6 still correlated independently with ANP (p < 0.05) after adjustment for the duration of diabetes and BUN." (PMID 34663293, 2021).